GJB2 (gap junction protein beta 2)
Diseases named in the same sentence as GJB2 in open-access papers (continued):
Sharing a sentence is not in itself a finding about the gene and the disease.
hearing loss (continued). "To assess if common or divergent mechanisms are at the root of GJB2-linked hearing loss, we expressed several mutants in cochlear-relevant HEI-OC1 cells derived from the developing organ of Corti." (PMID 32300592, 2020). "GJB2 gene (that encodes Cx26) mutations are causal of hearing loss highlighting the importance of Cx26-based channel signaling amongst the supporting cells in the organ of Corti." (PMID 32300592, 2020). "After excluding mutations in the most common ARNSHL gene, GJB2, by Sanger sequencing, genetic screening for a panel of genes responsible for hereditary hearing impairment performed in 9 individuals with ARNSHL from unrelated Iranian consanguineous pedigrees." (PMID 32864763, 2020). "It has long been puzzling that mutation screening of GJB2 in a large proportion (6–15%) of patients with autosomal recessive hearing loss would identify only one pathogenic mutant allele." (PMID 31992338, 2020). "Approximately 135 different hearing loss mutations in the GJB2 gene have been identified that span the entire amino acid polypeptide sequence of Cx26." (PMID 32300592, 2020). "The mutations in the GJB2 gene (13q12.11, MIM 121011) encoding transmembrane protein connexin 26 (Cx26) account for a significant portion of hereditary hearing loss worldwide." (PMID 32708339, 2020). "Most (92.21%) of the patients with bi-allelic GJB2 mutations had severe-to-profound hearing loss, in which the c.235delC is the predominant causes (84.93%)." (PMID 31992338, 2020). "Our data confirms c.35delG as the most frequent GJB2 mutation causing non-syndromic hearing loss in the Argentinean population with a prevalence of 9.25% of the detected GJB2-mutated alleles." (PMID 33096615, 2020). "As in a series of literature, this case demonstrated that CI has brought about tremendous improvements in auditory skills as well as in speech production development in patients with profound hearing loss resulting from GJB2 mutations." (PMID 32027099, 2020). "Clinically, mutations and/or deletions in GJB2 (encoding Cx26) and/or GJB6 (encoding Cx30) are responsible for nearly 50% of congenitally acquired hearing loss with ~135 different mutations in GJB2 causing hearing loss." (PMID 32393745, 2020). "Mutations in Cx genes (particularly GJB2, which encodes Cx26) cause approximately half of all cases of congenital hearing loss in newborns." (PMID 31827424, 2019). "The prevalence of GJB2-associated hearing loss was quite variable, ranging from 0% in South Africa to 40~50% in Eastern Europe25." (PMID 30733538, 2019). "Variants in the GJB2 gene are the primary cause of ARNSHL andresponsible for 5-43% of nonsyndromic hearing loss in different ethnicities." (PMID 30816908, 2019). "The severity of GJB2-associated SNHI varies from late-onset mild hearing loss to congenital, severe-to-profound deafness, and is highly dependent on the genotypes." (PMID 31581539, 2019). "Of 37 participants who reported a family history of hearing loss, three had a GJB2 gene variant; five reported consanguinity, of which only one had a GJB2 gene variant." (PMID 29773520, 2019). "In conclusion, our results show that STRC deletions are the second most common cause of mild-to-moderate hearing loss after the GJB2 gene, which accounts for the majority of genetic hearing loss." (PMID 30867468, 2019). "A total of 29 families with segregating recessive non-syndromic hearing impairment were tested for mutations in GJB2 and for the del(GJB6-D13S1830) mutation." (PMID 31731535, 2019). "As such, the prevalence of GJB2 variants in hearing loss varied widely across different regions even within a single country." (PMID 30733538, 2019). "Among the hereditary hearing loss, the c.235delC in GJB2 gene was identified as the most frequent pathogenic variant, followed by p.H723R in SLC26A4 in Japanese population." (PMID 31645975, 2019).
hearing loss (continued). "The cohort was also enriched with ARCs whose current or future pregnancies were at risk for conditions that are more frequent in the population, including fragile X syndrome, cystic fibrosis, and GJB2-related DFNB1 nonsyndromic hearing loss and deafness." (PMID 30310157, 2019). "Because the GJB2 mutation related hearing loss is late-onset, there remains a time window for both prevention and therapeutic intervention." (PMID 31562289, 2019). "Recent evidence suggests that the GJB2 genotype plays an important role in non‐syndromic hearing loss." (PMID 30693673, 2019). "In this study, by exome sequencing, a homozygous GJB2 c.235delC variant,known to be pathogenic, was found in an individual with hearing loss, inherited fromfirst-cousin normal-hearing heterozygous parents." (PMID 30816908, 2019). "Gap Junction Protein Beta 2 (GJB2) gene variant is a well-known disease-causing gene among patients with hearing impairment." (PMID 30989077, 2019). "The autosomal recessive inheritance of GJB2 mutations means that only the NSHL patients with homozygous or compound heterozygous pathological GJB2 mutations would present with hearing impairment." (PMID 30973918, 2019). "Although many new genes have been found, the most common genes associated with hearing impairment still are GJB2, SLC26A4, and mtDNA 12S rRNA." (PMID 30693673, 2019). "Of 100 patients with severe to profound sensorineural hearing loss, 14 had one or more among nine variants in the GJB2 gene other than 35delG, including three who were heterozygote for 35delG." (PMID 29773520, 2019). "In different parts of the world, mutations in the GJB2 gene are associated with nonsyndromic hearing loss, and the homozygous 35delG mutation (p.Gly12Valfs*2) is a major cause of hereditary hearing loss." (PMID 29773520, 2019). "The present study was designed to determine the prevalence and types of GJB2 mutations in a cohort of patients with hearing impairments from the Moravian-Silesian population of the Czech Republic." (PMID 30344259, 2018). "Seeman and Sakmaryova later estimated that this splice-site mutation was present in about 4% of pathogenic GJB2 mutations in Czech patients with hearing loss." (PMID 30344259, 2018). "Mutations in the GJB2 gene [which encodes connexin 26 (Cx26)] are the most common causes of hereditary hearing loss in humans, and previous studies showed postnatal development arrest of the organ of Corti in different Cx26-null mouse models." (PMID 29361521, 2018). "The 46 DXN families were further classified based on consanguinity and the role of GJB2/ GJB6 mutations in the incidence of hearing loss, as the principle of complementarity cannot be applied to this subgroup at the phenotypic level." (PMID 29921236, 2018). "Collectively, biallelic GJB2 mutations explained 15–20% of hearing loss cases, in some studies; in other studies, they explained a much higher proportion of GJB2-associated hearing loss (30–53%)." (PMID 30344259, 2018). "GJB2 mutations are the most frequent cause of non-syndromic recessive hearing loss across diverse populations." (PMID 30150563, 2018). "Here, we report a novel deletion (copy number variation: CNV) in the GJB2 gene observed in a Japanese hearing loss patient." (PMID 30455902, 2018). "The third possibility is that, instead of GJB2 mutations, hearing impairment is in fact caused by mutations in other deafness genes, and these “mono-allelic” patients are incidental carriers of certain GJB2 variants that are prevalent in the population." (PMID 30576380, 2018). "Mutations in the SLC26A4 gene are reported to be the most frequent cause of hereditary hearing loss in East Asia, and the second most common cause worldwide, after Connexin 26 (GJB2) gene mutations." (PMID 29739340, 2018). "GJB2 mutations are the most common cause for hereditary hearing loss in humans and are responsible for about a quarter of all cases of hereditary hearing loss." (PMID 29361521, 2018).
hearing loss (continued). "We found that GJB2 gene mutations frequently caused hearing loss in the Moravian-Silesian population, and their distribution was similar to that reported in other Caucasian European populations." (PMID 30344259, 2018). "GJB2 biallelic variants have been found in approximately 25% of infants diagnosed with hearing loss." (PMID 29634755, 2018). "In the present study, the routine screening is initiated with GJB2 analysis because mutations in this gene have been identified worldwide in patients with hearing impairment." (PMID 29568747, 2018). "In the majority of probands, mutations in GJB2, a frequent genetic cause of hearing loss, had been previously excluded." (PMID 30157177, 2018). "Pedigree analyses showed that both homozygous p.V37I variants, as well as compound heterozygous p.V37I with other GJB2 pathogenic variants, contributed to various phenotypes of hearing loss." (PMID 28489599, 2017). "Mutations in the GJB2 gene, which encodes the Connexin26 (Cx26) protein, are the most common cause of childhood hearing loss in American and European populations." (PMID 28513246, 2017). "The identification of additional dominant mutations in GJB2 further confirmed its key role in genetic hearing loss." (PMID 28102197, 2017). "Mutations of the GJB2 gene lead to disturbances in the functioning of connexin 26, causing hearing loss (HL) by impairing transfer of intracellular potassium ions within the inner ear." (PMID 27177978, 2017). "Mutations in the genes encoding Cx26 (GJB2) and Cx30 (GJB6) cause non-syndromic inherited deafness, and alterations in the GJB2 gene are the most common etiology of childhood hearing loss in American and European populations." (PMID 28513246, 2017). "In this ADNSHL family with 16 affected members at the time of study, 11 affected members had consistent phenotypes (high-frequency hearing impairment) and genotypes (GJB2 c.524C > A mutation carriers)." (PMID 28102197, 2017). "With the exception of SLC26A4 and GJB2 mutations, mutations in genes linked to hearing loss are extremely rare and can be effectively evaluated by WES31." (PMID 28383030, 2017). "Loss of function in both SLC26A4 and GJB2 have been implicated in syndromic and non-syndromic hearing loss." (PMID 28222800, 2017). "Among 88 cochlear implantees with autosomal recessive non-syndromic hearing loss, subjects with GJB2 and SLC26A4 mutations were excluded." (PMID 29072634, 2017). "The offspring of an affected individual with the GJB2 mutation in Family 304 had a 50% chance of inheriting the altered gene, except for IV:22 and the four noise-induced hearing loss members." (PMID 28102197, 2017). "At the same time, mutations in GJB2, which encodes connexin 26, are the most common cause of congenital hearing impairment." (PMID 27177978, 2017). "Pathogenic variants in the gap junction protein beta-2 (GJB2) gene are the most common cause of hearing loss." (PMID 28489599, 2017). "The carrier rate of GJB2 gene mutations – 7.1 % (~1 in 14) was identified in the group of healthy participants and a high frequency of GJB2-related hearing loss was estimated in our population." (PMID 26896187, 2016). "The contribution of GJB2 gene mutations in hearing loss in the population of Yakutia (45.55%) is the highest among all previously studied regions in Asia." (PMID 27829488, 2016). "The results of the detection suggest that GJB2 mutations appear to be a major cause of congenital hearing loss in Linyi." (PMID 27247933, 2016). "GJB2 mutations are the most common causes of non-syndromic deafness and more than 100 GJB2 mutations are linked with hearing impairment." (PMID 26927086, 2016). "Mutations in the SLC26A4 gene are the second most frequent cause of human hereditary HL, after mutations in the GJB2 gene, accounting for ~ 10% of all hereditary hearing impairment cases." (PMID 27082237, 2016).
hearing loss (continued). "Digenic mutations leading to hearing loss have been reported in previous studies and include GJB2/GJB6, GJB2/GJB3, and KCNJ10/SLC26A4." (PMID 26832775, 2016). "Regarding the onset of hearing loss, mutations in GJB2 and SLC26A4 were principally found in the early-onset group." (PMID 27627659, 2016). "Pathogenic variants in the GJB2 gene, encoding connexin 26, are known to be a major cause of hearing impairment (HI)." (PMID 27224056, 2016). "Kenneson A, Braun KVN, Boyle C. GJB2 (ÿonnexion 26) variants and nonsyndromic sensorineural hearing loss: a HuGE review, Genet Med." (PMID 27829488, 2016). "Individuals with hearing loss received GJB2 (GenBank ID: NG_008358.1) genotyping, performed by the clinical diagnostic Stanford Molecular Pathology laboratory, as part of routine medical care." (PMID 27761313, 2016). "A total of 104 patients (30.68%) were confirmed to be associated with hereditary hearing loss caused by GJB2 mutation: 49 homozygotes (42 with the c.235delC allele, 4 with c.299_300delAT, and 3 with the c.109G>A allele) and 55 compound heterozygotes." (PMID 27247933, 2016). "Pathogenic variants in the GJB2 gene (gap junction protein beta 2, 13q12.11) encoding connexin 26 (Cx26) are known to be a major cause of congenital hearing impairment (HI) in many countries." (PMID 27224056, 2016). "We applied logistic regression analysis to evaluate the chances of identifying the two GJB2 gene mutations if profound/severe hearing loss vs moderate/mild hearing loss was diagnosed." (PMID 26896187, 2016). "The c.35delG mutation of GJB2 was previously reported to be the most prevalent mutation (21%) in a cohort of north Indian population with hearing loss." (PMID 26043044, 2015). "The most frequent causative genes for AR hearing loss, in order of frequency, are GJB2, SLC26A4, MYO15A, OTOF, CDH23, and TMC1, with at least 20 mutations of each reported." (PMID 26664958, 2015). "In this study, the relative genetic contribution of the CDH23 mutation to nonsyndromic arSNHL was estimated in a Korean pediatric hearing loss cohort, and the genetic load of GJB2 and SLC26A4 was documented." (PMID 26264712, 2015). "A few mutations in GJB2 have also been reported to cause dominant nonsyndromic or syndromic hearing loss." (PMID 26061099, 2015). "In particular, connexin 26 (Cx26, GJB2) mutations are responsible for ~50% of non-syndromic hearing loss, which is the highest incidence of genetic disease." (PMID 26074771, 2015). "To date, GJB2 gene mutations give rise most notably to syndromic and non-syndromic hearing loss with comparable carrier frequencies to other prevalent genetic diseases such as cystic fibrosis and sickle-cell anemia." (PMID 26439696, 2015). "In the present study, we revealed a high prevalence (27.13%) of GJB2 mutations in Chinese hearing loss patients, which is compatible with other reports." (PMID 26043044, 2015). "GJB2 is the most common causative gene for hereditary hearing loss in many populations worldwide, and most of the GJB2 sequence variations described to date were localized in the coding region (The Connexin-deafness Homepage." (PMID 26043044, 2015). "Mutations in Gap Junction Beta 2 (GJB2) have been reported to be a major cause of non-syndromic hearing loss in many populations worldwide." (PMID 26043044, 2015). "GJB2 sequencing was carried out for 130 probands with sporadic or autosomal recessive non syndromic hearing loss." (PMID 26061264, 2015). "More than 110 different GJB2 mutations causing hearing loss have been identified in humans, where the hearing loss can vary from profound to mild." (PMID 26664958, 2015). "Data for 122 patients and 132 controls indicated that GJB2 rs3751385 (C/T) was associated with hearing loss susceptibility, in agreement with previously published research." (PMID 26075227, 2015). "Mutations in GJB2, which encodes for connexin 26, are the most common cause of hearing loss amongst this population." (PMID 26185573, 2015).
hearing loss (continued). "Sequence analysis of GJB2 in the current cohort identified 16 families with mutations in this gene segregating with hearing loss." (PMID 24949729, 2014). "A majority (10/11) of subjects carrying dominant GJB2 mutations exhibited palmoplantar keratoderma in addition to hearing impairment." (PMID 24945352, 2014). "To date, more than 91 different mutations in the GJB2 gene have been proven in connection with hearing loss (connexin-deafness homepage, which lists, however, only mutations characterized until 2003)." (PMID 24551843, 2014). "Mutations in GJB2 gene coding protein connexin 26 (Cx26) in homozygous and compound-heterozygous states are responsible for a significant part of inherited autosomal recessive forms of hearing loss in different populations." (PMID 24959830, 2014). "In China, almost 50% of patients with nonsyndromic hearing loss carry the GJB2 or SLC26A4 mutations." (PMID 24337325, 2014). "Results of this study demonstrate the limitations of screening as only the most prevalent mutations of the GJB2 gene were used to identify causative factors in hearing loss patients." (PMID 24337325, 2014). "Over 90 mutations in the GJB2 gene that encodes Cx26 give rise to both syndromic and non-syndromic deafness that accounts for approximately half of congenital cases of hearing impairments." (PMID 24988191, 2014). "Genetic analysis revealed that among the etiology of non-syndromic hearing impairment, GJB2, SLC26A4, and mitochondrial m.1555A > G mutations accounted for 18.0%, 13.1%, and 0.9%, respectively." (PMID 24612839, 2014). "The results suggested that the c.257C>G (p.T86R)/c.605ins46 mutations in the GJB2 gene provides a novel molecular explanation for the role of the GJB2 gene in hearing loss." (PMID 24337325, 2014). "The gene most commonly involved in hearing loss worldwide is GJB2, while SLC26A4 is also frequently involved in congenital hearing impairment." (PMID 24767429, 2014). "Both c.257C>G and c.605ins46 are rare GJB2 mutations that have previously been reported to segregate with autosomal recessive hearing loss exclusively in East Asian populations." (PMID 24337325, 2014). "Mutations of the GJB2 gene encoding the connexin 26 (Cx26) gap junction protein, which is widely expressed in the inner ear, are the primary cause of hereditary non-syndromic hearing loss in several populations." (PMID 24624091, 2014). "GJB2 mutations are the most common cause of childhood hearing loss worldwide, followed by SLC26A4 mutations." (PMID 24164807, 2013). "delGJB6-D13S1830 mutation is the second most frequent genetic cause of non-syndromic prelingual hearing impairment in the Spanish population and a digenic pattern of inheritance involving GJB2 mutations and delGJB6-D13S1830 mutation in GJB6 gene is sug-gested." (PMID 23503914, 2013). "Nonsyndromic inherited hearing impairment caused by mutations in GJB2, SLC26A4, or mtDNA 12S rRNA typically account for 33.8% of the cases of deafness in areas of China." (PMID 24341454, 2013). "Similar to that of the GJB2 gene mutations, the association between mtDNA mutations and hearing loss has also a special ethnic and regional difference." (PMID 23826813, 2013). "In summary, the results of our study indicate that the mutation spectrum and prevalence of GJB2 and mtDNA 12S rRNA genes in Jiangsu patients with hearing loss is similar to other areas of China." (PMID 23826813, 2013). "More practically, we suggest checking the p.V37I variant of GJB2 in children with mild to moderate hearing impairment that segregates in a manner compatible with autosomal recessive inheritance." (PMID 23637863, 2013). "The most widely studied example of connexin-associated disease has been Cx26 (GJB2) in hearing loss." (PMID 23967136, 2013). "Among the 22 probands from group I segregating milder hearing loss, four subjects (18.2%) carried the p.V37I variant of GJB2, either as one of two mutant alleles (three subjects) or as a single heterozygote (one subject)." (PMID 23637863, 2013).